FOXP3 (forkhead box P3)
Diseases named in the same sentence as FOXP3 in open-access papers (continued):
Sharing a sentence is not in itself a finding about the gene and the disease.
tumor (continued). "In serous ovarian cancer, inflammatory infiltration with CD8+CD4+FoxP3+ cells, a high degree of tumor vasculature, and overexpression of VEGF were favorable prognostic factors." (PMID 32488850, 2020). "In oral squamous cell carcinoma, the upregulation of FOXM1 has been shown to correlate with tumor growth, and FOXP3-mediated immune modulation appeared to potentiate the anti-tumor effectiveness of regulatory T cell-based immunotherapy." (PMID 32967107, 2020). "Recent studies elucidating the interplay between the tumor microenvironment and colonic microbiome have identified two distinct subpopulations of immunosuppressive and proinflammatory FOXP3+ T-cells." (PMID 32099066, 2020). "Mechanisms by which the FOXP3 complex regulates infiltration of the tumor microenvironment by other immune cells at the molecular level are still not fully understood." (PMID 32316975, 2020). "FOXP3 from cancer cells and regulatory T cells (Treg) cells suppresses immune responses and allows for tumor escape." (PMID 33224866, 2020). "A high density of FoxP3+ TILs in the TN indicated an immunosuppressive environment, so it was the reason for tumour recurrence." (PMID 33170901, 2020). "The increase in Foxp3 expression in colorectal tissues and peripheral blood correlates with an increasing degree of tumor malignancy and lymph-node metastasis." (PMID 32674255, 2020). "The expression levels of Foxp3 and TGFβ in transplanted tumor tissues were detected by quantitative fluorescence PCR." (PMID 33204731, 2020). "From the 49 tumor specimens, 35 (74%) and 15 (31%) were scored as FoxP3-positive in interstitial lymphocytes and in tumor cells, respectively." (PMID 32123292, 2020). "Immunofluorescence staining and flow cytometry were performed to observe the infiltration of CD8+ T cells and FoxP3+ T cells in tumor tissues." (PMID 32366856, 2020). "It has also been revealed that by Ipilimumab therapy, Foxp3+ Tregs in the tumor tissues of melanoma patients remarkably decreased specifically in clinical responders." (PMID 33519807, 2020). "The positive percentage of CD4, CD8, and FOXP3 at the periphery of LM and tumor‐liver interface were 2.29, 1.08, and 0.09% in median, respectively." (PMID 32135041, 2020). "There were fewer Foxp3-positive cells in the post-vaccination tumor compared with that of pre-vaccination." (PMID 32164575, 2020). "In conclusion, our results demonstrate that PD-L1 high expression on VECs inhibits the infiltration of CD8+ T cells, whereas promotes the aggregation of FoxP3+ T cells into tumor tissues, thus becoming an “immunosuppressive barrier”." (PMID 32366856, 2020). "Cancer-Foxp3 was positively correlated with Tregs accumulation in tumour tissues derived from PDAC patients and was associated with tumour volume and prognosis." (PMID 32680511, 2020). "FOXP3 was expressed in tumor cells from 22 cases (10 mild expressions, 8 moderate expressions, and 4 strong expressions), while 30 cases were negative for FOXP3." (PMID 33274240, 2020). "Foxp3+ γδ regulatory T (γδ Treg) cells promote tumor growth by various mechanisms and induce immuno-senescence." (PMID 32802845, 2020). "Gene transfer of IL-27 enhanced T cell infiltration into the tumor as well as T cell effector functions and led to a significant reduction in FoxP3+ Treg in tumors to 6.63% compared to 39.8% of FoxP3+ Tregs with control vector." (PMID 32674264, 2020). "Anlotinib downregulated PD-L1 expression on VECs through the inactivation of AKT pathway, thereby improving the ratio of CD8/FoxP3 inside tumor and remolding the immune microenvironment." (PMID 32366856, 2020). "We found that the tumor volume formed by the Hep3B-FOXP3 was smaller than that form by Hep3B cells, indicating that FOXP3 inhibited tumor growth in vivo (P = 0.001)." (PMID 33116119, 2020). "FoxP3 is a marker of Tregs, and a large number of FoxP3+ Tregs are related to a poor prognosis of multiple types of tumours." (PMID 32076456, 2020).
tumor (continued). "The proportion of CD4+CD25+Foxp3+ Treg in transplanted tumor tissues was detected by flow cytometry." (PMID 33204731, 2020). "Within BC, Miyashita and colleagues report that neoplasms with a high number of Treg cells have a significantly poorer prognosis when compared with the ones that were scarce in FOXP3+." (PMID 33143050, 2020). "FOXP3 is an interesting and promising molecular therapy target, since it seems to be an independent factor of aggressive behavior when it is expressed in tumor cells and, also, is deeply involved in modulating immune defense of the host." (PMID 33274240, 2020). "A possible explanation for our results is that FOXP3+ cells can suppress tumor-promoting proinflammatory cytokines that lead to malignancy." (PMID 32498695, 2020). "This group also demonstrated that tumor Tregs exhibited a phenotype of increased abundance of Foxp3, as well as other transcription factors including Eos, IRF-4, Satb1, and Gata-1." (PMID 32425930, 2020). "PD-L1 is also involved in the maintenance and induction of tumor-associated Tregs by inhibiting the Akt/mTOR signaling cascade, which promotes differentiation and switch from naive CD4+ TL to induced CD4+ CD25+ FOXP3+ Tregs." (PMID 33381116, 2020). "FoxP3+ T-cells are involved in maintaining immunological tolerance toward host tissues and considered to be suppressors of anti-tumor immune responses." (PMID 32785290, 2020). "Currently, IHC-based detection of various TIL-specific markers (e.g., CD3, CD8, FOXP3) on serial sections of tumor tissue is one of the primary approaches for profiling the lymphocyte infiltrates in the TME." (PMID 33013886, 2020). "FOXP3 has important value in suppressing killing ability of cytotoxic T cells on target tumor cells." (PMID 33614473, 2020). "First, because of the limited number of Foxp3+ MAIT cells detected in the tumor infiltrate samples, additional studies will be needed to more properly assess the function of these cells." (PMID 33205061, 2020). "The high infiltration of FOXP3+ TIL and the presence of PD-L1+ immune cells were associated with tumor recurrence in patients with pure DCIS." (PMID 32216826, 2020). "According to previous studies, the ratio of CD8/FoxP3 is considered to be one of the markers of tumor immune microenvironment, and patients with a high ratio of CD8/FoxP3 always have a better prognosis." (PMID 32366856, 2020). "Clinical frailty was associated with higher frequencies of exhausted/senescent (CD27−CD28− and/or CD57+) terminally differentiated CD8+ cells in the blood and with increased tumor infiltration by FOXP3+ cells." (PMID 33024560, 2020). "On days 7 and 14 after radiation, the expression levels of CD86+, CD4+, CD8+, and Foxp3+ cells, and levels of Ki-67+ protein were detected by immunohistochemistry, and the tumor necrosis rate was calculated." (PMID 32942998, 2020). "And tumor infiltrating Bcl6–/– Treg cells exhibited markedly decreased expression of Foxp3, while upregulating the expression of TFs and cytokines related to other lineages, including Tbet, RORγt, GATA3, IL4, and IL17, suggesting a weakened lineage stability." (PMID 32477338, 2020). "Tumor infiltration FOXP3+ cells correlated with reduced survival time and reduced relapse free survival (RFS)." (PMID 33062410, 2020). "Although most of the negative cases had a mitotic index of 2 or 3 mitoses/mm2, tumors with a high mitotic index showed an increased expression of FOXP3 in tumor cells than tumors with a low proliferation rate." (PMID 33274240, 2020). "For example, a single i.t. injection of IL-12-loaded microspheres with and without GM-CSF-loaded microspheres induced apoptosis and elimination of tumor-infiltrating CD4+CD25+Foxp3+ T suppressor cells." (PMID 33178203, 2020). "Tumor evoked B regulatory cells (tBregs) play a primary role in lung metastases by the conversion of resting anti-tumor CD4+ T cells into FoxP3+ expressing Treg cells through the paracrine action of TGFβ and CCL22 expressed from lung." (PMID 33414786, 2020).
tumor (continued). "T-cell exhaustion (CD8+ PD-1+/CTLA-4+) and treatment-induced depletion of regulatory T-cells (CD4+ Foxp3+/CTLA-4+) was seen in tumor or blood in 5/5 patients with clinical benefit, but only in one non-responder." (PMID 32681091, 2020). "In certain cancers, CD4+FOXP3+ T cells in tumor tissue were classified into two functional subtypes by the level of FOXP3 expression." (PMID 32377339, 2020). "Their presence is highly statistically significant when correlated with FOXP3 expression in tumor cells (t test, two-tailed P value = 0.0043)—tumors with a high expression of FOXP3 will have a high number of infiltrating FOXP3-positive lymph cells." (PMID 33274240, 2020). "Our meta-analysis confirmed that high densities of TILs, CD3+TILs, CD4+TILs, CD8+TILs and CD20+TILs in the tumour nest are favourable prognostic biomarkers for patients with NSCLC, and Foxp3+TILs in the tumour stroma are a poor prognostic biomarker." (PMID 33170901, 2020). "But how Bcl6 regulate Foxp3 expression and function of tumor infiltrating Treg cells remains unsolved in our study." (PMID 32477338, 2020). "In further analysis of the infiltration of immune cells, we found that compared with the control group, anlotinib and combination treatment group significantly inhibited the aggregation of CD45+ CD4+ CD25+ FoxP3+ T cells in the tumor tissues." (PMID 32366856, 2020). "In contrast, as one of the paradoxically functional components of the tumour-related immune system, Foxp3+ TILs are considered to be the most specific Treg marker involved in maintaining immune tolerance to the host." (PMID 32758195, 2020). "FoxP3+T cells are preferentially attracted to the tumor microenvironment with the help of chemokines and this transforms them to not only highly proliferative but also highly transformative." (PMID 32626535, 2020). "Our group evaluated the effect of silencing Foxp3 on antitumor efficacy of a genetically modified tumor cell vaccine against B16 mouse melanoma cells." (PMID 32079263, 2020). "Tumor-reacting CD8+ T-cells and consequent IFNγ production cause expression of PD-L1 and other immunosuppressive proteins, such as indoleamine 2,3-dioxygenase (IDO1) and Foxp3, on tumor cells as a feedback mechanism, as shown in melanoma cells." (PMID 33260538, 2020). "For example, Wnt signaling attenuates the suppressive activity of T regs by disrupting Foxp3 transcription activity, and autocrine inhibition of Wnt signaling in NK cells mediates tumor immune evasion by downregulating the expression of activating ligands." (PMID 31914456, 2020). "We evidence reduced primary tumor growth associated with increased immune responses, reduced metastatic progression, and enhanced response to anti‐CTLA4 monotherapy in Foxp3‐fGFP mice when compared to WT controls." (PMID 31729760, 2020). "On the other hand, the percentage of Foxp3 + Treg in CD4 + T cells within the tumour was significantly decreased with the administration of anti-PD-1 antibody (Control; 39.5 ± 6.7%, 4H2; 21.2 ± 3.2%." (PMID 31914969, 2020). "A significant correlation between IDO1 expression and increased FoxP3+ tumor-infiltrating lymphocytes was found in a cohort of PTMCs." (PMID 33986723, 2020). "Using multi-parameter analysis of immune checkpoints such as PD-L1, CD8, and FOXP3 to study the interactions between cell types can provide a more comprehensive immune phenotype in the tumor microenvironment and help predict prognosis and precise treatment." (PMID 33364188, 2020). "In this study, we compared the effects of low-dose CTX at different time points on the expression of the anti-inflammatory cytokines IL-10 and TGF-β1, T-cell subsets including CD4+CD25+Foxp3+ T cells, and tumor immunity in mice." (PMID 32104586, 2020). "Again, the most frequent immune targets in CD4+ T cells from patients with GBM, in descending order, isolated from the tumor microenvironment were A2aR > PD-1 > CTLA-4 > CD39 > TIGIT > FOXP3 > LAG-3 > CD160 > TIM3 > KIR > CD73." (PMID 32721947, 2020).
tumor (continued). "Their transcriptomic and flow cytometry analyses demonstrate that ST2 expression induces a more activated and migratory phenotype in FoxP3 positive Tregs, and results in an intensively accumulation in the tumor microenvironment." (PMID 32246094, 2020). "CD8 + T cells play a central role in anti-tumor immunity whereas accumulation of Foxp3 + regulatory T cells (Treg) dampens effector function." (PMID 31974367, 2020). "As shown with biaxial plots, we identified a population of CD4+ Foxp3+ tumor-infiltrating MAIT cells and validated them by flow cytometry on additional CRC tumor infiltrate samples." (PMID 33205061, 2020). "It was revealed that F. nucleatum-high tumors are characterized by increased tumor growth and invasion, an immune microenvironment with decreased FoxP3+ T cells through the tumor and a high proportion of M2-macrophages in the tumor center." (PMID 33375686, 2020). "In cancer, CD4+FoxP3+ Tregs migrate to tumors to suppress anti-tumor immune responses, allowing cancer cells to persist." (PMID 33375291, 2020). "Collectively, the expression of tumor FOXP3 can inhibit the growth of HCC via suppressing c-Myc directly or indirectly via interacting with Smad2/3/4." (PMID 33116119, 2020). "Tumor regression is correlated with an inhibition of FOXP3 regulatory T cells in the presence of an increased number of dendritic cells." (PMID 33274240, 2020). "The proportion of CD4+CD25+Foxp3+ Treg in the transplanted tumor tissues of mice in the solanine treatment group was significantly lower than that in the control group." (PMID 33204731, 2020). "In a mouse model of HCC, both TGF-β and IL-10 have been found to be associated with tumor progression, and in vitro TGF-β has been found to promote the differentiation of Foxp3+CD4+ Tregs." (PMID 32488850, 2020). "The frequency of total CD4+FOXP3+ lymphocytes as well as regulatory T cells was significantly greater in patients with at least one tumor-involved lymph node compared to those with tumor-free nodes (P = 0.026 and P = 0.036, respectively)." (PMID 33305045, 2020). "In terms of immunosuppressive factors, Treg cells (primarily CD4+ FOXP3+ T lymphocytes) and TAMs (primarily M2 macrophages) are clusters of cells that impede tumor immunity via complex regulation." (PMID 32595757, 2020). "Tumor-derived exosomes were shown to mediate the conversion of CD4+ CD25− T cells into CD4+ CD25high FOXP3+ regulatory T cells with enhanced expression of Fas ligand, IL-10, TGF-β1, CTLA-4, granzyme B, and perforin." (PMID 32499786, 2020). "FOXP3 is a critical marker of Treg cells which suppress cytotoxic T cells attacking tumor cells (Facciabene, Motz & Coukos, 2012)." (PMID 32419983, 2020). "Recently, a cell population identified as CD4+ Foxp3-PD-1hi was demonstrated to suppress tumor-infiltrating and peripheral CD4+ and CD8+ effector T cells." (PMID 33008010, 2020). "A 2014 study showed that ART was capable of inhibiting orthotopic tumor growth in human cervical cancer cells while decreasing Foxp3 expression in T cells, and facilitated the reduction of Tregs." (PMID 32372963, 2020). "It has been demonstrated that 5–30% of CD4+Foxp3+Tregs expressed a high level of granzyme B in tumor environments." (PMID 33519807, 2020). "Previous evidence demonstrated that tumor-infiltrating lymphocytes, as well as Foxp3+ T cells, correlate with good prognosis in GC." (PMID 32025866, 2020). "Tumor microenvironment of R115 group showed an increase in number of CD8+ and CD141+ cells, PD-L1+ tumor cells, and FoxP3+ T regulatory cells with a decrease in the number of CD11b+ cells." (PMID 32050597, 2020). "CD4+Foxp3+ Tregs represented a large proportion of TILs in claudin-low tumours, and Tregs isolated from tumours were able to suppress effector T cell responses." (PMID 32680511, 2020). "The proportion of FOXP3+ Tregs and tumor infiltrating CD8+ T cells had positive relationship with patient prognosis and immune escape." (PMID 33364188, 2020).
tumor (continued). "Since the in vitro culture of CD4+ CD25high regulatory T cells under hypoxia also induced the expression of IL-17, the authors suggested that CRC-derived CD68+ cells attracted Foxp3+ Tregs at the tumor site where hypoxia induced their expression of IL-17." (PMID 32121394, 2020). "Macrophages, CD4+ T and FOXP3+ T cells are strong promoters of angiogenesis in tumours, explaining some of our findings." (PMID 32946040, 2020). "The systemic expansion of a CD4+ CD62Llow CD27- FOXP3- CD44+ CXCR3+ ICOS+ T-bet+ T cell subset in mice treated with anti-cancer cell immunoglobulins was correlated with tumor rejection." (PMID 33329566, 2020). "These consisted of miR‐326, miR‐155, p16INK4a, Gal‐9 and IP‐10 for age and p16INK4a, CD3+CD16+, CD8+CD57+, CD28+CD27−CD28− and whole tumor proportion of FOXP3+ cells for the G8 groups." (PMID 33024560, 2020). "In both compartments, FoxP3+ Treg number was significantly different according to tumor localization, with the highest number in oral and oropharyngeal regions (Kruskal-Wallis test; ST, p = 0.031; IT, p = 0.024)." (PMID 30781400, 2019). "We found that the frequency of CD4+Foxp3+ Tregs was increased in circulating and tumor-infiltrating lymphocytes from BC patients." (PMID 30718502, 2019). "CD4- and FOXP3-stained images were used to identify T-helper cell and Treg cell distribution in the tumor microenvironment." (PMID 31635338, 2019). "The TME of EGFR mutated NSCLC, as in other tumours, includes several cells of the immune system: tumour-associated macrophage (TAM), T cell CD4+, CD8+, regulatory T cell (Treg FOXP3+), and mast cells." (PMID 31554160, 2019). "As ectopic expression of FOXP3 in conventional T-cells confers an immunosuppressive phenotype, a strategy for targeting FOXP3 was developed to counteract imperfect immune responses against tumor cells." (PMID 31547627, 2019). "This emphasizes and upgrades the assumption that we previously published, namely that the combination of high FoxP3+ Treg infiltration and early tumor stage improve the prognosis of HNSCC patients." (PMID 30781400, 2019). "The expression levels of CD3, CD8, Foxp3, and programmed death-ligand 1 (PD-L1) in immune cells at the invasive margins of tumor tissues were evaluated by quantitative multispectral imaging." (PMID 31048714, 2019). "S1P1 expression was upregulated in BC tissues compared with tumor-adjacent tissues and was positively correlated with the density of tumor-infiltrated Foxp3+ Tregs." (PMID 30718502, 2019). "Tumor infiltrating Tregs were rapidly converted into Th17 cells, down-regulated FOXP3 expression and lost their suppressive capacity." (PMID 31354747, 2019). "We and other authors have demonstrated that patients with GC have an increased prevalence of both circulating and tumor-infiltrating CD4+CD25+FoxP3+ Tregs in comparison to the healthy population." (PMID 31417548, 2019). "Complementary FOXP3+/CD8+ cell ratio was suggested to reflect an immune evasion of a tumor, with its higher values in tumor center as compared with the peritumoral area." (PMID 31016433, 2019). "Fourteen days after i.v. tumour inoculation, disseminated tumour growth induced an increase of Tregs (Foxp3+CD25+ cells gated on CD4+) in the spleen from 6.8 ± 1.7% in naïve mice to 18.8 ± 3.6% in tumour-bearing mice." (PMID 31683642, 2019). "Like the B16-OVA, IR alone induced a significant increase in tumor-infiltrating FoxP3+CD4+ Tregs and a decrease in the ratio of CD8+ T/Tregs in the irradiated lung." (PMID 31704921, 2019). "The infiltration of Tbet+ Foxp3+ Tregs was strongly correlated with a concomitant tumor-specific and conventional type 1-oriented intratumoral T cell infiltrate." (PMID 30658697, 2019). "The complexity of the influence of tumour-infiltrating FoxP3+ cells is also illustrated by a recent study: Two phenotypically distinct subpopulations of these lymphocytes had a different effect on colon cancer prognosis." (PMID 30232514, 2019).